TSC1 (TSC complex subunit 1)
Diseases named in the same sentence as TSC1 in open-access papers (continued):
Sharing a sentence is not in itself a finding about the gene and the disease.
Obesity (continued). "Furthermore, conditional deletion of Tsc1, an upstream suppressor of mTORC1 in hypothalamic neurons (and in beta cells of the pancreas), induces hyperphagic obesity, and hypothalamic POMC neuron-specific deletion of Tsc1 results in the same phenotype." (PMID 25309497, 2014). "However in mice, chronic activation of the mTOR/S6K pathway by POMC neuron-specific deletion of TSC1, demonstrate leptin resistance, hyperphagia and obesity, presumably due to an alteration of the hypothalamic neurocircuitry of energy balance." (PMID 22291999, 2012). "Studies have shown that the methylation rate of the TSC1 promoter in the hypothalamus of obese rats is significantly increased, and inhibition of this methylation downregulates the expression of mTOR, thereby activating autophagy in the hypothalamus and alleviating the obesity phenotype." (PMID 36313328, 2022). "Therefore, we dare to speculate whether the methylation level of Tsc1 gene promoter is related to the abnormal expression levels of Tsc1-mTOR signaling in the hypothalamus, resulting in different obesity tendencies in rats." (PMID 33532487, 2020). "Therefore, we speculate that hypothalamic Tsc1 may regulate the feeding circuit via the mTOR signaling pathway, addressing the great significance to study the hypothalamic Tsc1-mTOR signaling pathway for better understanding the pathogenesis of obesity." (PMID 33532487, 2020). "Mice lacking Tsc1 in macrophages exhibited protection from HFD-induced obesity, glucose intolerance, and adipose tissue inflammation." (PMID 37153549, 2023). "The expression of Tsc1 in DIO rats is downregulated, the mTOR signal in the hypothalamus is activated, and obesity in rats occurred, while DIO rats, on the contrary, showed obesity resistance." (PMID 33532487, 2020). "We have also identified three obesity-related genes (CROT, TSC1, RIN3) that have not previously been implicated as determinants of BMI or obesity." (PMID 28445147, 2017). "The remaining three genes (CROT, TSC1, RIN3) have not been previously associated with BMI or obesity." (PMID 28445147, 2017). "Three SNPs [rs7808249 (G/A) of CROT, rs1076160 (A/G) of TSC1, rs8018360 (C/T) of RIN3] were related (P < 0.05 in at least one genetic model) to obesity, although there was no SNP significantly [P < 0.0011 (0.05/44)] associated with this condition." (PMID 28445147, 2017).
renal carcinoma (10 papers, 2008 to 2025). A carcinoma arising from the epithelium of the renal parenchyma or the renal pelvis. "Collectively, our findings indicate that CDK4/6 inhibitors can increase the level of the TSC1 protein in renal cancer cells and regulate its stability." (PMID 38890443, 2024). "Based on an analysis of 79 genes associated with renal cancer, we found that VHL, PBRM1, BAP1, SETD2, and TSC1 mutation rates were higher in all RCCs at 51%, 35%, 16%, 15%, and 13%, respectively." (PMID 37427096, 2023). "Additionally, RNF26 interacts with TSC1 and regulates the proliferation, migration, and angiogenesis of renal cancer cells through the mTOR signaling pathway." (PMID 38890443, 2024). "Established increased risk of renal cancer and/or melanoma is observed with BAP1 mutations responsible for BAP1-TPDS, PTEN-AKT1/2-PIK3CA induced PTEN-opathies, as well as mTOR signaling syndromes such as TSC1/2 tuberous sclerosis complex." (PMID 34067022, 2021). "The primary genes that control the process of metabolic reprogramming in renal cancer are Myc, VHL, PTEN, Akt, mTOR, and TSC1/2 48-52." (PMID 38169635, 2024). "As our specialist interest lies in renal cancer research we chose to apply our methodology for the modification of genes known to be deleted in human renal cancer (VHL and TSC1)." (PMID 26046460, 2015). "VHL, MET, folliculin (FLCN), tuberous sclerosis 1 (TSC1), TSC2, fumarate hydratase (FH) and succinate dehydrogenase (SDH) are known as renal cancer genes, and all are involved in pathways that respond to metabolic stress or nutrient stimulation." (PMID 24348776, 2014).
colorectal cancer (9 papers, 2014 to 2025). A primary or metastatic malignant neoplasm that affects the colon or rectum. "Clinical analysis revealed that reduced TSC1 expression was significantly associated with poor prognosis in patients with colorectal cancer." (PMID 41445741, 2025). "In conclusion, this study identifies TSC1 as a key regulator of tumor-associated sialylation and immune evasion in colorectal cancer." (PMID 41445741, 2025). "Although accumulating evidence has linked mTOR signaling to tumor immunometabolism, how TSC1 modulates glycosylation-dependent immune evasion in colorectal cancer remains largely unknown." (PMID 41445741, 2025). "The present study provides compelling evidence that TSC1 serves as a crucial molecular nexus linking mTORC1 signaling, sialylation metabolism, and immune regulation in colorectal cancer." (PMID 41445741, 2025). "This investigation systematically examined the clinical relevance of TSC1 in colorectal cancer and its mechanistic relationship with sialylation-mediated immune regulation through integrated analysis of TCGA datasets and experimental validation." (PMID 41445741, 2025). "TSC1 serves as a critical regulator of the mTORC1 signaling pathway with established roles in colorectal cancer pathogenesis." (PMID 41445741, 2025). "TG or GG genotype of TSC1 have been demonstrated to be used as a potential therapeutic target to predict the worse overall survival or disease-free survival in colorectal cancer." (PMID 34315829, 2021). "This study identifies TSC1 as a prognostic biomarker and defines the TSC1/mTORC1/glycosylation axis as a potential therapeutic target to improve immune suppression in colorectal cancer, providing fundamental insights for the development of precision immunotherapy strategies." (PMID 41445741, 2025). "A study by Lee and colleagues showed that STK11, PRKAA1, and TSC1 polymorphisms were associated with disease-free survival after diagnosis with colorectal cancer; they did not see an association with TSC2." (PMID 25541970, 2014). "This discovery has clear clinical translational value, particularly in colorectal cancer patients with TSC1 pathway abnormalities, where combining mTOR inhibitors may enhance the sensitivity to immune checkpoint therapy and expand the applicability of precision immunotherapy." (PMID 41445741, 2025). "Immunofluorescence analysis revealed decreased TSC1 expression alongside elevated levels of ST6GALNAC1 and PD-L1 in colorectal cancer tissues compared to adjacent normal tissues." (PMID 41445741, 2025). "Mutations in other components of the pathway, including PTEN, TSC1, PPP2R1A, and MTOR, were also significantly more frequent in CDX2-suppressed colorectal cancers." (PMID 39452477, 2024).
prostate carcinoma (9 papers, 2015 to 2022). A carcinoma that arises from epithelial cells of the prostate gland. "In prostate cancer, the frequency of TSC1 and TBC1D7 mutation or deep deletion is low (≤0.8% incidence), whereas TSC2 mutation and deep deletion are more frequent (1–1.8% and up to 4.2% of cases respectively)." (PMID 32630372, 2020). "There is a study showing that AKT3 can promote prostate cancer cell proliferation by regulating Akt, B-Raf, and TSC1/TSC2." (PMID 36593867, 2022). "The tumor suppressor role of TSC1 was also corroborated in prostate cancer and high-grade serous ovarian carcinoma." (PMID 32410883, 2020). "TSC1-deficient mice developed prostatic intraepithelial neoplasia (PIN) and later prostate carcinoma." (PMID 26318033, 2015). "In conclusion, our observations suggested that elevation of AKT3 promotes the proliferation of prostate cancers cells through regulation of Akt, B-Raf, & TSC1/TSC2." (PMID 26318033, 2015). "As overexpression of AKT3 decreased protein level of TSC1 and TSC2, we hypothesized that knockdown of TSC1 or TSC2 will enhance proliferation of prostate cancer cells." (PMID 26318033, 2015). "Down-regulation of TSC1 and TSC2 as well as up-regulation of B-Raf caused by elevation of AKT3 may therefore contribute to the increase of cellular proliferation and provide growth advantage for prostate cancer cells." (PMID 26318033, 2015). "Remarkably, up to 3%, 4%, and 7% of patients with prostate cancer also display TBC1D7, TSC1, and TSC2 high-level amplification respectively, yet the functional consequence is currently unclear." (PMID 32630372, 2020). "Our experimental results showed that AICAR enhances the expression of TSC1 and TSC2, whereas it reduces the expression of mTOR and MYC as well as decreases the phosphorylation of p70S6K in 22Rv1 prostate cancer cells." (PMID 30987073, 2019). "We discovered that the elevation of AKT3 promoted the proliferation of different prostate cancer cell lines via induction of AKT phosphorylation and B-Raf as well as the reduction of TSC1 and TSC2." (PMID 26318033, 2015). "As cDNA overexpression of AKT3 and siRNA knockdown of AKT3 showed opposite effects on phospho-AKT S473, phospho-AKT T308, B-Raf, TSC1 and TSC2, these proteins may play essential roles in the proliferation regulation of AKT3 in prostate cancer cells." (PMID 26318033, 2015). "However, by using logistic regression strategy, we found and validated that several VUS-containing genes (COL1A1, CSF3R, ERBB2, ITGB8, TSC1 and TSC2) in the PI3K-Akt signaling pathway can improve the predicting of metastasis in prostate cancer patients in Hong Kong and Shanghai cohorts." (PMID 36095024, 2022).
renal tumors (9 papers, 2010 to 2023). "However, renal tumors require somatic inactivation of the remaining TSC1 or TSC2 allele." (PMID 37627070, 2023). "Recently, comprehensive genomic analyses have described the relative frequency of tuberous sclerosis complex 1 and 2 (TSC1/TSC2) gene mutations, drawing attention to the role of the mammalian target of the rapamycin (mTOR) pathway in different renal tumors." (PMID 34069976, 2021). "The second hit is typically a small deletion of either 9q34 (TSC1) or 16p13.3 (TSC2), causing loss of heterozygosity (LOH), the incidence of which is reportedly high in kidney tumors (renal angiomyolipoma) but low in brain tumors (SEGA)." (PMID 34206526, 2021). "The relationship between TSC1/TSC2 complex and STAT3 was further confirmed in vivo by assessing the protein and mRNA levels of STAT3 in renal tumors and adjacent normal renal tissues from Tsc2+/- mice." (PMID 31949495, 2020). "Concurrently, the current literature showed the presence of mTORC1 pathway alteration (TSC1/TSC2/mTOR/RHEB) in a number of recently described renal tumors in patients without TSC mutations (i.e., in sporadic tumors in patients without germinal mutation of TSC1 or TSC2)." (PMID 35203531, 2022).
brain tumors (8 papers, 2015 to 2023). "TSC1-deficient brain tumors were intermixed with distinct cell populations, e.g., small cells with hyperchromatic nuclei and glial appearance, normal-sized cells with a spindle shape and long processes intersecting, and cells with balloon-like morphology." (PMID 33923449, 2021). "Because of the deficiency of Tsc2, the activity of the Tsc1/Tsc2 complex is decreased, leading to the overactivation of the mTOR pathway, which is the primary cause of TSC-related symptoms, including tumours of the brain, skin, heart, lungs, and kidney." (PMID 34576223, 2021).
Insulin resistance (8 papers, 2010 to 2025). Increased resistance towards insulin, that is, diminished effectiveness of insulin in reducing blood glucose levels. "In addition to generate a more robust impact on mTORC1 effectors, TSC1 loss is recognized to induce severe insulin resistance by promoting mTORC1-mediated feedback inhibition of PI3K." (PMID 28462079, 2017). "The development of insulin resistance secondary to TSC1 deletion represents a limitation of this model, as it is difficult to delineate the contribution of mTORC1 versus insulin resistance to the phenotype studied." (PMID 28462079, 2017). "TNFα and NF-κB suppress TSC1 inhibition of mTORC1, resulting in hyperactive mTORC1 activity, which contributes to insulin resistance." (PMID 20625397, 2010). "Hyperandrogenism can suppress AMPK—an upstream brake on mTORC1 through TSC1/2 and direct Raptor inhibition—while insulin resistance/hyperinsulinemia drive PI3K/AKT-dependent mTORC1 activation, jointly unleashing translational programs and attenuating FOXO-mediated restraint." (PMID 41301707, 2025). "Despite an increase in liver mass and the presence of insulin resistance, the Tsc1−/− mice showed no histologic or biochemical evidence of excessive TG accumulation in the liver compared with wild-type littermates." (PMID 21479224, 2011).
Kidney Cyst (8 papers, 2015 to 2024). Abnormal fluid filled sac within the kidney, either acquired or congenital. "A more recent report on Tsc1 inactivation in mouse principal cells showed that kidney cysts exhibited a gradual loss of Aquaporin 2 (AQP-2)-positive cells in their epithelium." (PMID 38028758, 2023). "Cell-specific loss of Tsc1 within nestin-expressing cells in adult mice leads to the formation of kidney cysts, renal intraepithelial neoplasia, and invasive papillary renal carcinoma." (PMID 29184052, 2017). "In this present study, we sought to examine the ontogeny of kidney cysts in Tsc1/Car2 dKO and Tsc1/Foxi1 dKO mice." (PMID 38731991, 2024). "We conclude that Car2 inactivation temporarily decreases the kidney cyst burden in Tsc1 KO mice but the cysts increase with advancing age, along with enhanced Foxi1 expression." (PMID 38731991, 2024). "In this present study, we examined the impact of aging on the kidney cyst burden in Tsc1/Car2 dKO mice and included age-matched Tsc1/Foxi1 dKO mice." (PMID 38731991, 2024). "A similar cell phenotype was observed in kidney cysts in mice with pericyte-specific inactivation of TSC1." (PMID 38028758, 2023). "Both molecules exhibit enhanced expression at the mRNA and protein levels in kidney cysts in TSC1 KO mice." (PMID 38028758, 2023). "Recent studies on kidney cysts in various mouse models of TSC, including mice with principal cell- or pericyte-specific inactivation of TSC1 or TSC2, have identified a unique cystogenic mechanism." (PMID 38028758, 2023). "This is in stark contrast to Tsc1/Foxi1 dKO mice, which showed a remarkable absence of kidney cysts at both 47 and 110 days of age." (PMID 38731991, 2024). "A surprising finding is that Dermo1-mediated Tsc1 ablation failed to produce kidney cyst in young or old mice." (PMID 30696882, 2019). "To discern the molecular basis of kidney cystogenesis in Tsc1 KO mice, we analyzed and contrasted the RNA transcriptomes in: 1) Tsc1 single KO mice which have numerous cysts and cyst adenomas; and compared it to 2) Tsc1/Foxi1 dKO mice that do not exhibit any kidney cysts." (PMID 38028758, 2023). "The prevalence of kidney cysts in TSC alone is between 30 and 50 %, more frequent in TSC2 than TSC1, especially when the TSC2 gene harbours a nonsense or frameshift mutation." (PMID 26077033, 2015).
pancreatic cancer (8 papers, 2015 to 2023). "Consistent with this concept, our data demonstrates that RYGB surgery significantly attenuates the deficiency of TSC1 on mTORC1 activation in either the pancreatic cancer tissue or its neighboring normal pancreatic tissues." (PMID 30305629, 2018). "RYGB surgery significantly attenuated the deficiency of TSC1 on mTORC1 activation in either the pancreatic cancer tissue or its neighboring normal pancreatic tissues." (PMID 30305629, 2018). "Recent studies have reported that in a number of human cancers, including pancreatic cancer, TSC1 exhibits tumor suppressive effects." (PMID 37124502, 2023). "For example, miR-130a is upregulated in oral squamous cell carcinoma and suppresses expression of TSC1, a tumor suppressor gene, and an miR-301a inhibitor suppresses pancreatic tumor growth in a xenograft model." (PMID 34830336, 2021). "In addition, a positive correlation between Tsc1 and Gadd45g expression was found in pancreatic cancer patients from The Cancer Genome Atlas (TCGA) dataset." (PMID 35211358, 2022). "For prognostic prediction, we developed an immune-related prognostic risk model (IRPM) based on four immune-related prognostic genes in pancreatic cancer, RHOF, CEP250, TSC1, and KIF20B." (PMID 38203311, 2023). "Our findings suggest that miR-301a activates two major cell proliferation pathways, Tsc1/mTOR and Gadd45g/Stat3, in vivo, to facilitate development of inflammatory-induced PanIN and maintenance of PSC activation and desmoplasia in pancreatic cancer." (PMID 35211358, 2022). "GNB3, PPP2R3B and TSC1 were highly expressed in the LRS group, suggesting that these genes may be tumor suppressors of pancreatic cancer." (PMID 37124502, 2023).
polycystic kidney disease (8 papers, 2012 to 2023). A usually autosomal dominant and less frequently autosomal recessive genetic disorder characterized by the presence of numerous cysts in the kidneys leading to end-stage renal failure. "Compared with patients with a TSC1 mutation, those with TSC2 mutations had a higher occurrence of multiple renal cysts (33.6 vs. 13.3%) and polycystic kidney disease (4.7 vs. 0%)." (PMID 33041968, 2020). "To score for the epistatic interaction of Tsc1 and S6k1 in polycystic kidney development, we compared Ksp-Cre; Tsc1fl/fl with Ksp-Cre; Tsc1fl/fl; S6k1−/− kidneys." (PMID 32581239, 2020). "In addition to these findings, Tagln-mediated Tsc1 inactivation generated a phenotype similar to TSC with impaired development of several organs, polycystic kidney disease, and cardiac hypertrophy." (PMID 32927859, 2020).
Alzheimer disease (7 papers, 2021 to 2025). A progressive, neurodegenerative disease characterized by loss of function and death of nerve cells in several areas of the brain leading to loss of cognitive function such as memory and language. "These include for example the tuberous sclerosis complex-1 (TSC1) gene, which in recent years has been associated with TAU pathology in frontotemporal dementia and Alzheimer's disease, where loss-of-function TSC1 inclusions lead to an increase of TAU burden." (PMID 38554150, 2024). "Furthermore, the FTO-induced hypo-m6A levels have been shown to activate the TSC1-mTOR-Tau signaling pathway and increased apoptosis of dopaminergic neurons, which contributes to the pathogenesis of Alzheimer’s disease (AD) and Parkinson’s disease (PD), respectively." (PMID 33922187, 2021). "In Alzheimer's disease, TSC1 aggregates form in the absence of TSC2 in the CA1 region of the hippocampus, leading to increased inflammation, altered autophagy, β‐amyloid accumulation and cell death via mTOR." (PMID 39962362, 2025). "We find that knockdown of Tsc1 and mTor gene expression, does not significantly increase or decrease tau aggregate counts in rat neurons incubated with tau seeds extracted from human Alzheimer’s disease brains." (PMID 34127790, 2021).